BCL2 (BCL2 apoptosis regulator)
Diseases named in the same sentence as BCL2 in open-access papers (continued):
Sharing a sentence is not in itself a finding about the gene and the disease.
breast carcinoma (continued). "Moreover, diosgenin induced a significant loss of the mitochondrial membrane potential in breast cancer cells, and prominently affected cell death through down-regulation of the anti-apoptotic protein, Bcl-2." (PMID 31881805, 2019). "Finally, we observed heterogeneity by tumour subtype for the BCL2 SNP rs7236090, for which the minor allele was protective of breast cancer." (PMID 30601841, 2019). "The Bcl-2-associated death promoter BAD is a prognostic indicator for good clinical outcome of breast cancer patients; however, whether BAD affects breast cancer biology is unknown." (PMID 30635657, 2019). "Finally, we find that rs7236090 in BCL2 has the strongest protective effect associated with hormone receptor positive breast cancer subtype among women of East Asian descent." (PMID 30601841, 2019). "Treatment of MDA-MB231 breast cancer cells with low molecular weight fucoidan resulted in a significant decrease in anti-apoptotic proteins Bcl-2, Bcl-xl and Mcl-1 associated with the activation of caspases, mitochondrial dysfunction and alteration of Ca2+ homeostasis." (PMID 30621025, 2019). "Bcl-2 is well known as an anti-apoptotic oncogene in lymphomas, and this anti-apoptotic function may explain why Bcl-2 positivity has been associated with the chemoresistance and radioresistance of breast cancer cells." (PMID 30630524, 2019). "Bcl-2 expression is associated with lymph node metastases of bladder and gastric cancer, liver metastases of colorectal cancer and lymphovascular invasion of patients with breast cancer." (PMID 31921862, 2019). "Several studies have measured the expression of a single apoptosis-associated protein, such as BAX and BCL-2, by immunohistochemistry, flow cytometry or quantitative real-time PCR analyses and correlated its expression with the prognosis of mammary tumors and lymphoma." (PMID 31676831, 2019). "For example, Ki-67, STK15, Survivin, Cyclin B1, and MYBL2 have all been associated with breast cancer proliferation; Stromelysin 3 and Cathepsin L2 have been associated with invasion; and ER, PR, Bcl2, and SCUBE2 have been associated with responsiveness to Estrogen." (PMID 29848291, 2018). "Herein, we also observed that gAcrp significantly decreased cancer cell growth and significantly increased caspase‐7 enzyme activity, caused TTP and AUF1 induction, and suppressed BCl‐2 expression in MCF‐7 breast cancer cells with a pattern similar to that observed in hepatic cancer cells." (PMID 30524947, 2018). "Isothiocyantaes, such as benzyl isothiocyanate and sulforaphene, efficiently reduce the survival of prostate and breast cancer cells, what is associated with the induction of ROS, disruption of mitochondrial membrane potential and downregulation of Bcl-2 protein." (PMID 29508061, 2018). "Interestingly, Bcl-2 is commonly associated with ER-positive breast tumors and has been recognized as a favorable prognostic marker in breast cancer." (PMID 29876007, 2018). "Bcl-2 has emerged as an important prognostic factor for the risk of breast cancer recurrence." (PMID 29254147, 2017). "BCL2 is associated with the long term survival of breast cancer." (PMID 24637666, 2014). "Associations between Bcl-2 expression and clinicopathologic features in male breast cancer." (PMID 23573235, 2013). "Bcl-2 expression has been cited as a favorable prognostic marker and its expression has been shown to be associated with improved survival among patients with breast cancer." (PMID 24124558, 2013). "In addition, we also chose 4 breast cancer cell lines to investigate the association between this polymorphism and Bcl-2 expression in vitro." (PMID 21457555, 2011). "Further research is necessary to elucidate whether BCL-2 (-938C > A) polymorphism can serve as a prognostic biomarker for breast cancer patients." (PMID 21457555, 2011).
breast carcinoma (continued). "In summary, we can conclude that AA genotype of BCL-2 (-938C > A) may be one susceptible genotype for breast cancer, and this genotype is associated with the nodal status of breast cancer." (PMID 21457555, 2011). "Finally, we identified that screen-detected tumours were more likely to show higher expression of BCL2, an anti-apoptotic protein whose expression is associated with improved survival from breast cancer." (PMID 19773756, 2009). "High BCL2 tumor expression was associated with better outcome in endocrine-treated breast cancers." (PMID 18928543, 2008). "However, the present study is the first to evaluate bcl-2 in high-risk patients with stage III breast cancer treated with a homogenous adjuvant regimen, i.e., AC/T." (PMID 17430582, 2007). "However, the expression of bcl-2 in breast cancer has been found to be associated with favorable prognostic factors such as smaller tumor size, ER positivity, and low nuclear grade." (PMID 17430582, 2007). "However, in breast cancer specimens, bcl-2 expression is associated with markers of better differentiation, like lower grade lesions, ER positivity, and a low proliferation status." (PMID 17430582, 2007). "The Bcl-2 protein expression was demonstrated to be associated with a high proliferative activity as measured by the S phase fraction in breast and colon cancers or the 3H thymidine labeling index in breast cancer." (PMID 16839413, 2006). "In addition to its anti-apoptotic function, BCL2 has a suggested role in neuro-endocrine differentiation in colon carcinomas and its downregulation is associated with poor prognosis in breast cancer." (PMID 17069663, 2006). "Moreover, the dysregulation of other apoptosis-associated proteins such as BCL-2, survivin and caspases may affect apoptosis in breast cancer as well as in other neoplasms." (PMID 38891056, 2024). "A recent study suggested that resveratrol may upregulate miR-122-5p, consequently causing cell-cycle arrest of adriamycin-resistant breast cancer cells by targeting apoptosis and cell cycle key regulators such as B-cell lymphoma 2 (Bcl-2) and cyclin-dependent kinases (CDKs)." (PMID 35912113, 2022). "Similarly, another study also found that AA genotype of BCL-2 (−938C>A) may be associated with breast cancer susceptibility and increase the breast cancer risk in Chinese women, which was also inconsistent with our findings." (PMID 33708254, 2021). "In addition, the functional DOX nanoparticles could cause apoptosis of the drug-resistant breast cancer cells by activating the pro-apoptotic proteins Bax and Bid and suppressing the anti-apoptotic protein Bcl-2." (PMID 25605018, 2015). "While Bcl-2 is a biomarker of resistance to both chemotherapy and radiotherapy, the association of Bim with the anti-apoptotic Bcl-2 protein may explain why Bcl-2 overexpressing lung and breast cancer cells are more sensitive to microtubule-targeting agents such as paclitaxel and vinorelbine." (PMID 26405162, 2015). "We and others have previously reported that hsa-miR-195 negatively regulates BCL2 expression and we also demonstrated that over-expression of hsa-miR-195 not only caused an increase in apoptosis but also augmented the death inducing effect of etoposide in breast cancer MCF-7 cells." (PMID 26632252, 2015). "As shown by immunoblot analysis, breast cancer cells treated with α-mangostin result in decrease of anti-apoptotic Bcl-2 and a concomitant increase of pro-apoptotic Bax proteins, thereby caused a significant increase in the Bax/Bcl-2 ratio that favors apoptosis." (PMID 24894151, 2014).
breast carcinoma (continued). "Consequently, the overexpression of β2-M transcripts may cause up-regulation of the Bcl-2 transcripts in breast cancer, and restrain apoptosis in breast cancer cells." (PMID 25292288, 2014). "Thus, the BCL-2 (-938C > A) polymorphism may be an indicator of lymph nodal metastasis in female breast cancer." (PMID 21457555, 2011). "Since Bcl-2 protein has been reported to contribute much to breast malignancy development (or progression), we conducted this study to investigate whether this polymorphism functioned as a modifier of breast cancer development." (PMID 21457555, 2011). "In contrast, our study reveals that the prognostic effect of BCL2 protein expression is time independent and BCL2 continues to be associated with favourable outcome over time, increasing its potential clinical value given the frequent occurrence of late relapses (particularly in ER+ breast cancer)." (PMID 20664598, 2010). "Moreover, we show that loss of expression of the anti-apoptotic molecule Bcl-2 is involved in apoptosis induced by breast cancer cell line supernatants and demonstrate that exogenous conditioning with CD40L (and IL-12) protects blood DCs from apoptosis through sustained expression of Bcl-2." (PMID 16417648, 2006). "Thus, loss of bcl-2 expression in breast cancer is associated with a range of molecular markers of poor prognosis and may define part of an ER-negative, EGFR-positive phenotype." (PMID 8286195, 1994). "The review also covers emerging candidates like an miR-221 inhibitor and various strategies for breast cancer, such as targeting Bcl-2, KRAS, and specific miRNAs." (PMID 42076082, 2026). "Other studies have also shown that Bcl‐2 overexpression prevents the uptake of 99mTc‐MIBI in breast cancer." (PMID 41513589, 2026). "Flavonoids modulate estrogen signaling, inhibit aromatase, reduce BCL-2, and activate caspases in breast cancer." (PMID 41346617, 2025). "The rationale for choosing Cyclin D1 and BCL2 genes for gene expression research is that overexpression of cyclin D1 and BCL2 has been reported in over 50% of human breast cancers of all histological types." (PMID 40283136, 2025). "In HER2 + breast cancer, BCL-2 expression is negatively correlated with c-erbB2 protein immunostaining and is a marker of poor prognosis." (PMID 40104496, 2025). "Isoliquiritigenin decreased MMP and induced apoptosis in breast cancer cells by modulating Bcl-2 proteins and activating caspase cascades." (PMID 40862778, 2025). "In line with our findings, in a comprehensive meta-analysis of over 5000 cases, BCL2 immunohistochemistry concluded BCL2 as an independent positive prognostic factor across breast cancers." (PMID 40806359, 2025). "Dihydroartemisinin (DHA)‐loaded liposomes enhanced the circulation time of Epirubicin and improved its efficacy in different breast cancer cells by reducing Bcl‐2 activity, promoting Beclin‐1 release, and activating Bax." (PMID 40529859, 2025). "Cell viability and angiogenesis decreased in ethyl acetate extract-treated breast cancer cells, whereas apoptosis/cell cycle arrest increased as a result of down-regulating Bcl-2 expression and up-regulating Bax, SOD, CAT, and caspase 3/8 expression." (PMID 40699792, 2025). "In breast cancer cells, ROS can undermine the protein-protein interactions between Bcl-2 and apoptosis-promoting members of the Bcl-2 family, such as Bax and Bak, thereby fostering the production of apoptotic pores within mitochondrial membranes." (PMID 39925807, 2025).
breast carcinoma (continued). "The Bcl‐2/Bax signaling pathway is recognized as one of the key pathways influencing the apoptosis of breast cancer cells." (PMID 40497373, 2025). "Aside from hematopoietic malignancies, the BCL2 gene exhibits activity in various types of solid tumors, including but not limited to breast cancer, lung cancer, pancreatic cancer, and sarcoma." (PMID 39735667, 2025). "In RES‐treated breast cancer cells, the Bax/Bcl‐2 ratio decreases while caspase‐8 activity increases, thereby activating the extrinsic apoptotic pathway." (PMID 40502812, 2025). "The combination of 10 μM RES and 3 Gy ionizing radiation induced apoptosis in MCF‐7 breast cancer cells by reducing the Bax/Bcl‐2 ratio." (PMID 40502812, 2025). "DHA‐EPI liposomes induced excessive autophagy in breast cancer cells by reducing Bcl‐2, enhancing Beclin‐1 release, and activating Bax." (PMID 40529859, 2025). "F-H: ROC curves for PSMB8 (F), PSME2 (G), and BCL2 (H) across the different subtypes of breast cancer (Cluster 1 and Cluster 2) in the TCGA-BRCA dataset." (PMID 41403941, 2025). "Several studies in our analysis have also observed that triterpenes increased Bax/Bcl-2 ratio and cleaved caspase-3 levels, two apoptosis markers, effects confirmed in human breast cancer cell lines such as MCF-7 and MDA-MB231 as well." (PMID 41322296, 2025). "VACAgNPs demonstrated concentration‐dependent modulation of apoptosis markers across all breast cancer cell lines, with distinct Bax/Bcl‐2 ratios and caspase activation patterns." (PMID 41234608, 2025). "These derivatives demonstrate strong inhibition of cell viability in colorectal and breast cancer cell lines by downregulating Bcl-2 and upregulating Bax expression." (PMID 40430886, 2025). "From this selection, two DNAzymes, DNZ-15 and DNZ-35a, emerged as potent candidates, displaying robust cleavage activity in vitro and significant BCL-2 knockdown in liver carcinoma and breast cancer cells." (PMID 40643466, 2025). "Recent data have shown that rosmarinic acid decreased breast cancer stem cell viability, up-regulated apoptosis, decreased Bcl-2/Bax proteins ratio, and down-regulated miR-30a-5p." (PMID 39859345, 2025). "Mahanine induces apoptosis via mitochondrial pathways, increases ROS, activates caspases 3, 7, and 9, upregulates Bax, downregulates Bcl-2, and targets estrogen receptor alpha and CDKs in leukemia and breast cancer cells." (PMID 41346617, 2025). "The upregulation of cyclin D1 and BCL2 via ERα signaling correlates with an enhanced proliferative response in breast cancer cells." (PMID 40283136, 2025). "Antisense drugs (antisense oligonucleotides) that inactivate Bcl-2 mRNA to prevent the production protein have been developed for breast cancer treatments." (PMID 40055250, 2025). "The Bax/Bcl-2 ratio has been established as a strong prognostic indicator in breast cancer patients, with higher ratios correlating with better survival outcomes." (PMID 39796221, 2025). "In the mitochondrial (intrinsic) pathway, orbitides and lignans increase the Bax/Bcl-2 ratio, induce cytochrome c release, and activate caspases-9 and -3, leading to DNA fragmentation and cell death in gastric, leukemia, and breast cancer cell lines." (PMID 41228480, 2025). "Niclosamidetreatment in breast cancer has been shown to inhibit cell proliferationby modulating apoptosis-related proteins such as cleaved caspase-3and Bcl-2, ultimately leading to cell death." (PMID 40521512, 2025).
breast carcinoma (continued). "In breast cancer, NF-κB-driven overexpression of Bcl-2 enhances chemoresistance and metastatic potential, whereas pharmacological suppression of NF-κB (e.g., via chrysophanol) downregulates Bcl-2 and cyclin D1, restoring apoptotic sensitivity." (PMID 40562870, 2025). "Bcl-2 expression was downregulated remarkably in Carvacrol receiving animals relative to those with the untreated breast cancer (***P ≤ 0.001 vs. normal) where Bcl-2 was notably up-regulated." (PMID 41369848, 2025). "Cyclin D1 and BCL2 gene overexpression is identified in the earliest stages of breast cancer development, such as ductal carcinoma in situ, and is maintained in all phases of metastasis." (PMID 40283136, 2025). "Outside of TNBC, BCL-2 inhibitors have been explored in HR-positive breast cancers with mixed results." (PMID 40242242, 2025). "In breast cancer cells, some oncogenes often show irregularity in cancer cells, such as Bcl-2, EGFR, and HER-2." (PMID 39779635, 2025). "It has been demonstrated that niclosamide modulatesapoptotic proteinsBax and Bcl-2 in breast cancer stem cells." (PMID 40521512, 2025). "Studies have shown that ursolic acid, oleanolic acid, betulinic acid and liquid ambaric acid can induce apoptosis of breast cancer cells by regulating Bax and Bcl-2." (PMID 40076586, 2025). "In grade I to III breast cancer histology, the expression of BCL-2 showed a downward trend with significant differences." (PMID 40104496, 2025). "In breast cancer cells, hsa-miR-195 induces apoptosis by targeting genes such as Bcl-2 and FASN; however, aberrant activation of MYC can antagonize the pro-apoptotic effect of miR-195 by upregulating anti-apoptotic proteins like Bcl-xL." (PMID 41210882, 2025). "Simultaneous inhibition of HSP90 and BCL-2 offers a strategy to target these interconnected mechanisms, destabilize oncogenic proteins, and promote apoptosis in resistant breast cancer cells." (PMID 39779635, 2025). "Overexpression of MORC4 significantly increases the expression of BCL-2 in breast cancer cells and increases their resistance to adriamycin, 5-fluorouracil and cisplatin." (PMID 40070565, 2025). "Numerous studies have also revealed that proteins related to the apoptotic pathway, such as BAX, Bcl-2 and Caspase-3, play significant roles in the occurrence of malignant tumors such as esophageal cancer, breast cancer, pancreatic cancer and prostate cancer." (PMID 41411247, 2025). "Clinically, there have been trials assessing the efficacy of BCL-2 inhibitors in combination with other anti-cancer agents in breast cancer." (PMID 40242242, 2025). "Critical in the upregulation of oncogenes such as MYC and BCL‐2, driving malignant transformation and cancer cell survival in numerous cancer types, including breast cancer and lymphomas." (PMID 40959208, 2025). "In this study, seaberry treatment resulted in a significant increase in the Bax/Bcl-2 ratio in rat mammary tumors at both dose levels, accompanied by elevated expression of cleaved caspase-3 in treated groups." (PMID 40371330, 2025). "A previous study found that 25 μg/mL aerial parts of A. absinthium extract activated caspase-7 and elevated Bcl-2 protein in breast cancer cells (MCF-7 and MDA-MB-231)." (PMID 39770489, 2024). "(2021) demonstrated that NK‐EVs loaded with BCL‐2 siRNAs effectively inhibited the overexpression of BCL‐2 in breast cancer cells, significantly enhancing tumour cell killing." (PMID 39328262, 2024). "The reduction in BCL2 further sensitized the cells to apoptosis, supporting the use of this combination therapy as a promising approach for breast cancer treatment." (PMID 40190668, 2024).